RNU6-288P (RNA, U6 small nuclear 288, pseudogene)
Gene: Small nuclear RNA gene on chromosome 17 (63,573,242 to 63,573,345, reverse strand). Ensembl gene ENSG00000200560.
Homologues: Orthologues: chimpanzee U6 (96% identical), macaque U6 (92% identical), mouse Gm23462 (80% identical). Paralogues in human: RNU6-836P (84% identical), RNU6-263P (83% identical), RNU6-38P (83% identical), RNU6-539P (83% identical), RNU6-1038P (82% identical), RNU6-1145P (82% identical), RNU6-140P (82% identical), RNU6-16P (82% identical), RNU6-25P (82% identical), RNU6-29P (82% identical), RNU6-33P (82% identical), RNU6-356P (82% identical), and 1288 more.